BCL11A (BCL11 transcription factor A)
Diseases named in the same sentence as BCL11A in open-access papers (continued):
Sharing a sentence is not in itself a finding about the gene and the disease.
thalassemia (16 papers, 2013 to 2025). An inherited blood disorder characterized by a decreased synthesis of one of the polypeptide chains that form hemoglobin. "Among the 5 intronic polymorphisms in the BCL11A gene screened, the mutant T allele of rs1427407 (G → T) polymorphism, was significantly higher in the β-thalassemia intermedia group as compared to the thalassemia major group (P: 0.002, OR 5.6, 1.84–17.22)." (PMID 34686692, 2021). "The foremost article, published in Science, explores the role of BCL11A as a potential regulator of HbF expression, offering a new target for the treatment of thalassemia." (PMID 39726529, 2024). "Three genetic factors, α-thalassemia, rs11886868 in BCL11A and rs9389268 in HBS1L-MYB were account for 75% of the phenotype severity." (PMID 33990643, 2021). "The frequency of BCL11A is on higher side in thalassemia patients." (PMID 37680845, 2023). "A thalassemia severity score (TSS) was developed from 890 homozygous β-thalassemia patients of the Mediterranean basin using these different genetic modifiers including sex, β-thalassemia mutations, α-thalassemia, the Xmn1-HBG2, rs1427407 and rs1018957 in BCL11A and rs9399137 in HBS1L-MYB17." (PMID 33990643, 2021). "For example, a therapeutic enhancer in thalassemia, the half-E box/GATA1 binding site located in the BCL11A locus, is responsible for the erythrocyte expression of BCL11A, a key repressor of infant γ-globin expression." (PMID 35832085, 2022). "Recently, a designed targeted gene panel, which included all eight globin genes and validated modulators (KLF1, BCL11A, and MYB), was applied in molecular screening and clinical genotyping in thalassemia." (PMID 30809867, 2019). "The most studied genetic modifiers affecting the severity of SCD are the level of HbF expression, BCL11A, HBS1L-MYB, and coinheritance of α-thalassemia." (PMID 23762099, 2013). "The variability in severity of thalassemias, especially β-thalassemia, involves many gene loci, some of which are directly involved with defects in α, β, or γ globin synthesis, whereas others, related to other genes such as KLF1, BCL11A." (PMID 32671092, 2020). "Lentiviral-mediated KLF1 knockdown of normal (n = 3) and HbE/β0-thalassemia (n = 3) erythroblasts revealed that the expression of the γ–globin gene suppressor BCL11A decreased due to the absence of KLF1, which in turn activates the γ–globin gene and elevates HbF levels." (PMID 34070036, 2021).
leukemia (15 papers, 2007 to 2025). A malignant (clonal) hematologic disorder, involving hematopoietic stem cells and characterized by the presence of primitive or atypical myeloid or lymphoid cells in the bone marrow and the blood. "The dysregulation of BCL11A disrupts downstream molecular pathways, contributing to the development of several hematological malignancies, particularly leukemias." (PMID 39857257, 2025). "High expression of BCL11A has been found in various hematopoietic diseases of the lymphatic and myeloid systems and in various types of leukemia." (PMID 39857257, 2025). "Previous studies showed that BCL11A has an oncogenic potential and can promote the development of leukemia in both lymphoid and myeloid lineages." (PMID 32625084, 2020). "In terms of downstream targets, in leukaemia, it has been shown that BCL11A abrogates p21 transcription possibly via direct regulation of SIRT1 (refs 41, 42)." (PMID 25574598, 2015). "The BCL11B/Rit1/CTIP2 gene was first identified in human chromosome 14q32.2, as a homologue to BCL11A/CTIP1, which is known to be involved in translocations in human leukemia." (PMID 17941976, 2007). "In pediatric ALL, patients with mixed-lineage leukemia rearrangement have a poor prognosis, and the upregulation of BCL11A expression may lead to mixed-lineage leukemia rearrangement ALL." (PMID 39857257, 2025).
type 2 diabetes (12 papers, 2011 to 2023). "Elevated expression of BCL11A in human beta cells was reported to be negatively correlated to insulin secretion, contributing to an increased risk of type 2 diabetes development, making this gene a prominent target for further studies." (PMID 37672078, 2023). "The two most significant DMPs were found in PTPRN2 and BCL11A, with the former being associated to type 1 diabetes in mice and the latter to type 2 diabetes in human males." (PMID 27279921, 2016). "Recent studies have established an association between BCL11A gene polymorphisms and a risk of type 2 diabetes (T2D)." (PMID 25009601, 2014). "One highly-ranked candidate regulator was Bcl11a, a gene previously linked by human GWAS studies to increased type 2 diabetes (T2D) risk." (PMID 25330008, 2014). "A recent analysis suggested that the same genetic variant alters risk of both type 1 and type 2 diabetes in five regions, near CENPW, CTRB1/BCAR1, GLIS3, BCL11A and THADA." (PMID 33830302, 2021). "A number of studies have recently shown that BCL11A is involved in β-hemoglobinopathies, hematological malignancies, malignant solid tumors, 2p15-p16.1 microdeletion syndrome, and Type II diabetes." (PMID 31654056, 2019). "In recent years, much progress has been achieved in investigating the roles of BCL11A in some diseases, including β-hemoglobinopathies, hematological malignancies, malignant solid tumors, intellectual disability, and Type II diabetes." (PMID 31654056, 2019). "BCL11A has been associated with type 2 diabetes mellitus, but prior work has not linked BCL11A to insulin regulation in mammals." (PMID 25101872, 2014). "Additionally, Tang and co-workers recently showed that blood cells from males with type 2 diabetes had increased methylation of BCL11A compared with healthy male controls." (PMID 25517766, 2014). "This protein has beenrelated to many diseases such as type II diabetes, intellectual disability,β-hemoglobinopathies, cancer, and hematological malignancies, but the mechanisms bywhich BCL11A is connected to these diseases are not yet completely understood." (PMID 35293553, 2022). "Therefore, we note that we identified differential methylation of single CpG sites within 7/59, two CpG sites in 2/59 (BCL11A, AKT2), and consistent changes in six CpG sites in 1/59 (KCNQ1) type-2 diabetes genes." (PMID 25651499, 2015). "Sites annotated to 10 candidate genes for type 2 diabetes, including DUSP9, BCL11A, HNF4A, and CDKN2B, and 7 candidate genes for related metabolic traits (for example, ATP11A, ADCY5 and IRS1) had differential DNA methylation in human pancreatic islets based on sex." (PMID 25517766, 2014). "Likewise BCL11A, a human orthologue of CG9650, has been associated with type 2 diabetes mellitus, but prior work has not linked BCL11A to insulin regulation in mammals." (PMID 25101872, 2014). "We did not replicate the finding that the chromosome regions near CENPW, GLIS3, BCL11A or THADA co-localised between type 1 and type 2 diabetes (H4PP CENPW=0.12, GLIS3=0.29, BCL11A=0.28, THADA not examined as no type 1 diabetes association existed in the region [FDR=0.07])." (PMID 33830302, 2021).
Intellectual disability (10 papers, 2016 to 2025). "We identified nine individuals with intellectual disability with de novo mutations in BCL11A: three missense and six loss of function (LoF)." (PMID 27453576, 2016). "Besides its canonical role in hematopoiesis and repression of fetal hemoglobin in adults, BCL11A has neurodevelopmental roles, and haploinsufficiency causes intellectual disability and autism." (PMID 41001472, 2025). "Haploinsufficiency of this gene has been associated with intellectual disability in a large clinical study, with the phenotype recapitulated in Bcl11a knockout mice, which was shown to be mediated through downstream transcriptional dysregulation in the hippocampus and cortex." (PMID 28093568, 2017). "Recently, mutations in BCL11A and BCL11B, two ultra-conserved zinc-finger transcription factors, have been associated with multiple cases of neurodevelopmental disorders, including developmental delay, autism spectrum disorder, intellectual disability, and structural brain alterations." (PMID 38392344, 2024).
laryngeal squamous cell carcinoma (9 papers, 2017 to 2025). A squamous cell carcinoma that arises from the larynx. "We investigated the association between B-cell lymphoma/leukaemia 11A (BCL11A) rs11886868 and rs4671393 polymorphism, plasma BCL11A concentration, and the hazard of developing laryngeal squamous cell carcinoma (LSCC)." (PMID 28225775, 2017). "Studies have also revealed that high expression of BCL11A may be associated with neuroblastoma, glioblastoma, laryngeal squamous cell carcinoma, ovarian cancer, and prostate cancer." (PMID 31654056, 2019). "In LSCC (laryngeal squamous cell carcinoma) tissues, high levels of BCL11A were found and correlated with advanced lymphatic metastasis stages with poor prognoses." (PMID 40051609, 2025). "In laryngeal squamous cell carcinoma (LSCC), patients with advanced stage (III and IV) of LSCC had significantly higher BCL11A SNP odds ratios and higher plasma BCL11A concentrations than early stage (I and II)." (PMID 31654056, 2019).
B-cell chronic lymphocytic leukemia (8 papers, 2006 to 2025). "BCL11A (OMIM 606557) encodes B-cell chronic lymphocytic leukemia (CLL)/lymphoma 11A which is a zinc finger protein and regulates gene transcription by interacting with COUP-TF protein." (PMID 37937284, 2023). "The BCL11A gene is located on chromosome 2 and malfunctioning of BCL11A has been correlated with the development of B-cell chronic lymphocytic leukemia and other types of B-cell malignancies." (PMID 37298481, 2023). "The expression of BCL11A is significantly increased in patients with malignant B lymphoblastoma, providing a possible explanation for the resistance to apoptosis in patients with chronic lymphocytic leukemia." (PMID 39857257, 2025).
beta thalassemia (8 papers, 2014 to 2024). Beta-thalassemia (BT) is characterized by deficiency (Beta+) or absence (Beta0) of synthesis of the beta globin chains of hemoglobin (Hb). "In our study, we have performed Sanger sequencing on compound heterozygotes of Sickle beta thalassemia and Beta thalassemia patients to determine the different variants of target polymorphism (rs4671393) in BCL11A gene." (PMID 37936787, 2023). "In addition, the analysis also reveals that both Royal Kelantan Malay genomes shared 3 SNP markers; HBG1 (rs1061234), HBB (rs1609812) and BCL11A (rs766432) where all three markers were associated with beta-thalassemia." (PMID 27090252, 2014). "Our results showed that PE could efficiently install therapeutic corrections in a targeted and precise manner, suggesting that future PE3-induced beta-thalassemia therapy could be used to modify the BCL11A enhancer and induce precise corrections at each mutation site." (PMID 35682629, 2022).
lung carcinoma (8 papers, 2019 to 2025). "Further supporting a tumor-suppressor role are findings that down-regulation of BCL11A increases the resistance of cancer cells to radiation and loss of function of BCL11A is associated with genome instability in lung cancer." (PMID 31561579, 2019). "Currently, four ways of regulating BCL11A in lung cancer are known: by miRNA—miR-30a (silencing), amplification (activation), long non-coding RNA—DSCAM-AS1 (activation) and SOX2 (regulation at the transcription level)." (PMID 37372998, 2023). "Results showed that the expression level of BCL11A was higher in most cancers compared with normal tissues, such as cholangiocarcinoma, colon adenocarcinoma, esophageal carcinoma, lung cancer, kidney cancer, and so on." (PMID 35909289, 2022). "For lung cancer, BCL11A (targeted by chr2:60719002–60776000) overexpression predicts survival and relapse in non-small cell lung cancer." (PMID 34879086, 2021). "Another way of participation of DSCAM-AS1 in the pathogenesis of lung cancer is mediated through up-regulation of BCL11A, a proto-oncogene which is activated in lung cancer through different mechanisms such as gene amplification and over-expression of miR-30a." (PMID 34708048, 2021). "The expression of BCL11A was greater in patients with early stage cancer, suggesting that the activation of BCL11A proto-oncogene may occur at an early stage in lung cancer." (PMID 40051609, 2025). "Thus, BCL11A may play a role in diagnosing and predicting the prognosis of patients with lung cancer, particularly those with early stage lung squamous carcinoma." (PMID 40051609, 2025). "Therefore, the presence of mutations in genes encoding BAF proteins, e.g., BCL11A, is closely related to genomic instability in lung cancer, regardless of the subtype." (PMID 37372998, 2023).
non-small cell lung carcinoma (8 papers, 2013 to 2025). A group of at least three distinct histological types of lung cancer, including non-small cell squamous cell carcinoma, adenocarcinoma, and large cell carcinoma. "B-cell leukemia/lymphoma 11A (BCL11A) may be one of the potential biomarkers of non-small cell lung cancer (NSCLC)." (PMID 37372998, 2023). "However, the clinical significance of BCL11A in non-small cell lung cancer (NSCLC) remains unknown." (PMID 23758992, 2013). "DSCAM-AS1 enhances non-small cell lung cancer cell migration by elevating BCL11A, and DSCAM-AS1 may be a potential therapeutic target for non-small cell lung cancer." (PMID 35692369, 2022). "Amplification of BCL11A has also been demonstrated in lung squamous cell cancers (SCC), with the highest concentration of amplification found in samples from NSCLC (non-small cell lung cancer) without metastases." (PMID 40051609, 2025).
developmental delay (7 papers, 2016 to 2025). "Dias–Logan syndrome (DLS) is a rare condition caused by heterozygous germline BCL11A pathogenic variants associated with global developmental delay, distinctive facial features, and asymptomatic persistence of fetal hemoglobin." (PMID 40772033, 2025). "We also show evidence for a novel interaction between TBR1 and BCL11A, a regulatory protein implicated in a neurodevelopmental syndrome characterized by developmental delay, ID and language deficits." (PMID 30250039, 2018). "Furthermore, we characterized a putative interaction with BCL11A, a transcription factor that was recently implicated in a neurodevelopmental syndrome involving developmental delay and language deficits." (PMID 30250039, 2018). "Mutations of BCL11A and BCL11B, two closely related, ultra-conserved zinc-finger transcription factors, were recently reported to be associated with NDDs, including developmental delay, ASD, and ID, as well as morphogenic defects such as cerebellar hypoplasia." (PMID 38392344, 2024). "In addition, it was shown in two separate studies that individuals presenting with ASD and developmental delay had common microdeletions of BCL11A rendering them haploinsufficient for the gene." (PMID 29898395, 2018). "The lack of additional malformations in individuals with missense and LoF mutations in BCL11A indicates that adjacent genes or regulatory regions contribute to those features and that BCL11A may be a defining gene for the developmental delay/ID phenotypes of individuals with microdeletions." (PMID 27453576, 2016).
microcephaly (7 papers, 2016 to 2025). A congenital or acquired developmental disorder in which the circumference of the head is smaller than normal for the person's age and sex. "We show that Bcl11a haploinsufficiency in mice causes impaired cognition, abnormal social behavior, and microcephaly in accordance with the human phenotype." (PMID 27453576, 2016). "Nevertheless, postnatal microcephaly emerged as a common and previously underappreciated feature of BCL11A-IDD." (PMID 39448799, 2025). "Our results delineate an intricate pattern of genotype − phenotype correlation where BCL11A emerges as the main gene for autistic behavior while USP34 and/or XPO1 haploinsufficiency are mainly associated with microcephaly, hearing loss and IUGR." (PMID 36807877, 2023). "However, the BCL11A knockdown model of zebra fish developed microcephaly with reduced size, which was in contrast to macrocephaly in three cases." (PMID 37937284, 2023). "In agreement with previous reports, our investigation showed that BCL11A is particularly involved in cortical and cerebellar anomalies, and autistic behavior whereas USP34/XPO1 deletions are more associated with corpus callosum anomalies, microcephaly, IUGR, and hearing loss." (PMID 36807877, 2023). "Penetrant deletions for microcephaly outlined two SROs; SRO1 (p: 0.25, 2/8) including the BCL11A (cp: 0.23) and PAPOLG (cp: 0.13) genes, and SRO2 (p: 0.55, 6/11) overlapping the USP34 (cp: 0.77) and XPO1 (cp: 0.18) genes." (PMID 36807877, 2023).
myeloid leukemia (7 papers, 2006 to 2020). A clonal proliferation of myeloid cells and their precursors in the bone marrow, peripheral blood, and spleen. "The Bcl11a gene encodes a C2H2 zinc finger transcription factor, which acts as a retroviral insertion site (Evi9) in myeloid leukemia in BXH-2 mice." (PMID 32266150, 2020). "BCL11A is expressed in lymphohematopoietic cells, controls the development of B- and T-lymphocytes, and is a common site of retroviral integration in myeloid leukemia." (PMID 23506684, 2013). "Bcl11a was first discovered as a retroviral insertion site (Evi9) in myeloid leukemia tumors in the BXH-2 mouse." (PMID 25408871, 2012). "We also observed downregulation of transcription factors such as Mga and Tcf4, and myeloid leukemia related genes including Pml, Abl1, and Bcl11a in terminally differentiated granulocytes in conjunction with the expression of a group of granulocyte-enriched miRNAs." (PMID 24886830, 2014). "At the protein level, one notable difference between human and mouse appears to be the absence of BCL11A in the majority of human myeloid cell lines even though Bcl11a was initially described in myeloid leukemias arisen in the mouse BXH2 recombinant inbred strain." (PMID 16704730, 2006).